USP14 (ubiquitin specific peptidase 14)
Diseases named in the same sentence as USP14 in open-access papers (continued):
Sharing a sentence is not in itself a finding about the gene and the disease.
COVID-19 (2 papers, 2024 to 2025). A disease caused by infection with severe acute respiratory syndrome coronavirus 2. "Four upregulated common genes (DHX15, USP14, COPS3, TYK2) and one downregulated common feature gene (RIOK2) were identified and showed good diagnostic accuracy for T2DM and COVID-19." (PMID 38699234, 2024). "We constructed a PPI network and identified five common feature genes (DHX15, USP14, COPS3, TYK2, and RIOK) of T2DM and COVID-19 by extracting the core genes of the network." (PMID 38699234, 2024). "We identified five common feature genes between T2DM and COVID-19: DHX15, USP14, COPS3, TYK2, and RIOK2 (where DHX15, USP14, COPS3, and TYK2 were upregulated and RIOK2 was downregulated)." (PMID 38699234, 2024). "The roles of DHX15, USP14, COPS3, TYK2, and RIOK2 in T2DM and COVID-19 remain primarily unknown, emphasizing the importance of future research." (PMID 38699234, 2024). "In the validation dataset, the AUC values of DHX15, USP14, COPS3, TYK2, and RIOK were 0.922, 0.781, 0.812, 0.844, and 0.984, respectively, for T2DM, and 0.733, 0.687, 0.737, 0.782, and 0.632, respectively, for COVID-19." (PMID 38699234, 2024). "We identified five common feature genes (DHX15, USP14, COPS3, TYK2, and RIOK2) and their co-regulatory pathways between T2DM and COVID-19, which may provide new insights for further molecular mechanism studies." (PMID 38699234, 2024). "The results from the ROC curve analysis showed that DHX15, USP14, COPS3, TYK2, and RIOK had AUC values of 0.931, 0.917, 0.986, 0.903, and 0.917, respectively, for T2DM and AUC values of 0.960, 0.860, 1.0, 0.9, and 0.90, respectively, for COVID-19." (PMID 38699234, 2024). "We identified five common feature genes (DHX15, USP14, COPS3, TYK2, and RIOK2) and their co-regulatory pathways between T2DM and COVID-19, which may provide new insights for molecular mechanism studies." (PMID 38699234, 2024).
diabetic kidney disease (2 papers, 2023 to 2025). Progressive kidney disorder caused by vascular damage to the glomerular capillaries, in patients with diabetes mellitus. "Like other USPs, USP14 in podocytes also plays a deteriorative role in the pathogenesis of diabetic nephropathy." (PMID 36834633, 2023). "Similarly, independent studies identified USP36 in renal epithelial cells, and USP14, 15, and 22 in podocytes as complicating factors for diabetic nephropathy; however, the contribution of each USP to disease etiology is still unclear." (PMID 36834633, 2023). "The deubiquitinating enzymes UCH-L1, USP22, OTUD5, and USP14 act on PIRK3, TAK1, and SPAG5, respectively, and play a regulatory role in the pathophysiological process of diabetic kidney disease." (PMID 40225869, 2025). "USP14 was shown to directly stabilize the TGF-β receptor and lead to the activation of TGF-β signaling, which is accelerated in Müller cells of diabetic nephropathy patients." (PMID 36834633, 2023).
glioblastoma (2 papers, 2025). The most malignant astrocytic tumor (WHO grade IV). "The exogenous expression of ALKBH5 effectively rescued the impacts of USP14 KD on RNA m6A methylation, GSC proliferation, sphere-forming frequency in vitro, and the tumorigenicity of orthotopic glioblastoma xenografts." (PMID 39990235, 2025).
Glucose intolerance (2 papers, 2018 to 2023). Glucose intolerance (GI) can be defined as dysglycemia that comprises both prediabetes and diabetes. "Consistent with the phenotype in the HFD model, the knockdown of USP14 alleviated HFHC diet-induced glucose intolerance and reduced liver weight, lipid composition, and liver injury-associated enzyme activities." (PMID 37633951, 2023). "Due to a close association between hepatosteatosis and systemic insulin resistance, we observed a glucose intolerance and reduced insulin sensitivity in mice overexpressing USP14, as revealed by glucose and insulin tolerance tests." (PMID 30425250, 2018). "In addition, CYP2E1 inhibition alleviated IR and glucose intolerance in the Ad-USP14 group mice." (PMID 37633951, 2023).
Huntington disease (2 papers, 2016 to 2024). Huntington disease (HD) is a rare neurodegenerative disorder of the central nervous system characterized by unwanted choreatic movements, behavioral and psychiatric disturbances and dementia. "In Huntington’s disease, USP14 regulate ER stress-mediated cell death through IRE1, so USP14 may be a potential target for future treatment of HD and other cluster diseases." (PMID 38673794, 2024).
Insulin resistance (2 papers, 2018 to 2023). Increased resistance towards insulin, that is, diminished effectiveness of insulin in reducing blood glucose levels. "Likewise, hepatic USP4, 10, and 18 restore insulin resistance, whereas USP14 and 20 decrease it." (PMID 36834633, 2023). "Additionally, Usp14 silencing ameliorated insulin resistance in these mice." (PMID 36834633, 2023).
non‐alcoholic fatty liver disease (2 papers, 2023 to 2025). "In non‐alcoholic fatty liver disease, USP14 stabilises HSP90AA1 through deubiquitination, leading to increased levels of CYP2E1 and further exacerbating disease progression." (PMID 40988122, 2025).
oral squamous cell carcinoma (2 papers, 2018 to 2024). "Aberrant upregulation of the ubiquitin-specific protease 14 (USP14) has been found in some malignant tumors, including oral squamous cell carcinoma (OSCC)." (PMID 38388430, 2024).
Ovarian Tumor (2 papers, 2015 to 2021). "Many other de-ubiquitinases (DUBs), including USP14 and Ovarian Tumor (OTU, Ubiquitin Aldehyde Binding-1) OTUB-1 regulate tau (de)ubiquitination and control its proteasome clearance." (PMID 34564439, 2021). "These 33 enzymes represent >1/3 of all known human DUBs, and they include members of all four major DUB families—20 USPs (including CYLD, USP14 an USP8), 8 Ovarian Tumour (OTU) deubiquitinases (including Trabid and Cezanne), 3 ubiquitin C-terminal hydrolases (UCHs) and 2 JAMM metalloproteases." (PMID 25907794, 2015).
pancreatic ductal adenocarcinoma (2 papers, 2023 to 2025). An infiltrating adenocarcinoma that arises from the epithelial cells of the pancreas. "Additionally, USP14 deubiquitinates TAZ, enhancing its stability, and is positively regulated by TAZ-TEAD1/4, creating a feedback loop that drives tumor progression and metastasis in pancreatic ductal adenocarcinoma (PDAC) models." (PMID 39990235, 2025).
preeclampsia (2 papers, 2021 to 2025). Preeclampsia is a hypertensive disorder of pregnancy that is characterized by new-onset hypertension with proteinuria presenting after 20 weeks of gestation, and depending on mild or severe forms may initially present with severe headache, visual disturbances, and hyperreflexia. "The expression of USP14 in placental tissues from healthy donors and preeclampsia patients were determined by quantitative reverse transcription PCR assay." (PMID 34089575, 2021). "To investigate the potential relevance of USP14 in preeclampsia, we collected placental tissues from healthy donors (n = 30) and preeclampsia patients (n = 30)." (PMID 34089575, 2021). "The expression levels of USP14 and proinflammatory cytokine were substantially upregulated in placental tissues from preeclampsia patients." (PMID 34089575, 2021). "The messenger RNA (mRNA) levels of USP14 in these placental tissues were determined by RT‐qPCR, and the results showed that the expression levels of USP14 were significantly higher in placental tissues from preeclampsia patients than those from healthy donors." (PMID 34089575, 2021). "To further study the potential role of USP14 in preeclampsia, we aimed to knockdown of USP14 in trophoblast cell lines." (PMID 34089575, 2021). "To further confirm this result, we assessed the protein expression of USP14, p‐p65, and total‐p65 in placental tissues from healthy donors (n = 4) and preeclampsia patients (n = 4)." (PMID 34089575, 2021). "Our data implied that placental ischemia promotes upregulation of USP14, and the latter enhances the production of proinflammatory cytokines via activation of NF‐κB signaling, leading to worsening preeclampsia progression." (PMID 34089575, 2021). "Conversely, the expression of USP14 in placental tissue of patients with preeclampsia was significantly upregulated, knocking down or inhibiting USP14 significantly eliminated upregulation of NF-κB activation and production of pro-inflammatory cytokines (TNF-α and IL-1β)." (PMID 40040717, 2025). "We hypothesized that USP14 might influence preeclampsia progression by mediating the inflammatory response." (PMID 34089575, 2021). "We revealed that USP14 is significantly upregulated in placental tissues from patients with preeclampsia, suggesting USP14 may play a crucial role in the development or progression of preeclampsia." (PMID 34089575, 2021). "Developing drugs targeting USP14 may be beneficial for the prevention or treatment of patients with preeclampsia." (PMID 34089575, 2021). "This study, for the first time, revealed the potential role of USP14 in preeclampsia progression." (PMID 34089575, 2021). "The findings of this study may provide novel insight into USP14 in the regulation of preeclampsia." (PMID 34089575, 2021). "Thus, USP14 may serve as an excellent therapeutic candidate for developing strategies for preeclampsia prevention and management." (PMID 34089575, 2021). "The expression levels of USP14 and p‐p65, but not total‐p65, were substantially increased in preeclampsia patients' placental tissues compared to healthy donors' placental tissues." (PMID 34089575, 2021).
prion disease (2 papers, 2015 to 2016). A transmissible disease that is caused by a protein that is able to induce abnormal folding of normal cellular proteins, leading to characteristic spongiform brain changes, which are associated with neuronal loss without an inflammatory response. "Collectively, a better understanding about the regulation of PrPSc clearance caused by USP14 might contribute greatly to the development of therapeutic strategies for prion diseases." (PMID 26061634, 2015).
retinoblastoma (2 papers, 2024 to 2025). A malignant tumor that originates in the nuclear layer of the retina. "The aim of this study is to explore the function of USP14 on the sensitivity of retinoblastoma (RB) to cisplatin (DDP) and the underlying mechanism." (PMID 38819674, 2024). "The role of USP14 in regulating the sensitivity of retinoblastoma (RB) cells to cisplatin (DDP) and its potential mechanism were explored." (PMID 40497992, 2025).
Alzheimer disease (1 paper, 2015). A progressive, neurodegenerative disease characterized by loss of function and death of nerve cells in several areas of the brain leading to loss of cognitive function such as memory and language. "Consistent with the effects of USP14 upon the proteasome, these USP14 aptamers enhanced proteasome activity, and facilitated the degradation of Alzheimer’s disease (AD)-implicated tau proteins." (PMID 26041011, 2015).
amyotrophic lateral sclerosis (1 paper, 2019). Amyotrophic lateral sclerosis (ALS) is a neurodegenerative disease characterized by progressive muscular paralysis reflecting degeneration of motor neurons in the primary motor cortex, corticospinal tracts, brainstem and spinal cord. "A small molecule USP14 inhibitor IU1 and an inactive USP14 mutant C114A were shown to reduce the level of the amyotrophic lateral sclerosis (ALS) and dementia disease proteins TDP-43 and tau in mammalian cells." (PMID 31703099, 2019).
aortic valve stenosis (1 paper, 2025). Aortic valve stenosis (AVS) is a condition characterized by narrowing of the heart's aortic valve opening. "One study confirmed through gene expression analysis and molecular experiments that USP14's expression level is significantly elevated in samples from patients with aortic valve stenosis." (PMID 40988122, 2025). "In summary, this study reveals the critical role of USP14 in aortic valve stenosis through bioinformatics and experimental validation." (PMID 40988122, 2025). "The expression of USP14 and CDK4 was significantly higher in aortic valve stenosis (AVS) tissues compared to control (CON) tissues." (PMID 40988122, 2025). "In the pathological process of aortic valve stenosis (AVS), the regulation of USP14 on cell proliferation, apoptosis and fibrosis may involve multi‐dimensional molecular mechanisms." (PMID 40988122, 2025). "In aortic valve stenosis, the mechanism of USP14's action is not yet fully understood." (PMID 40988122, 2025).
autosomal dominant retinitis pigmentosa (1 paper, 2020). Autosomal dominant retinitis pigmentosa (RP) is an autosomally dominant inherited retinal dystrophy leading to progressive loss of the photoreceptors and retinal pigment epithelium and resulting in blindness usually after several decades. "Overexpression of USP14 restored the levels of rhodopsin-1 (Rh-1) protein in the Drosophila model of autosomal dominant retinitis pigmentosa (ADRP) and suppressed the retinal degeneration in the model." (PMID 33053617, 2020). "USP14 restored the levels of rhodopsin-1 protein in a Drosophila model for autosomal dominant retinitis pigmentosa and suppressed the retinal degeneration in this model." (PMID 33053617, 2020). "The present study shows the role of Drosophila USP14 under ER stress and ER stress related disease, autosomal dominant retinitis pigmentosa." (PMID 33053617, 2020).
brain injury (1 paper, 2022). Acute and chronic (see also brain INJURIES, CHRONIC) injuries to the brain, including the cerebral hemispheres, CEREBELLUM, and brain STEM. "Previous studies have shown that microglial exosomal miR-124 can downregulate USP14 to reduce neurodegeneration and promote synaptic growth in mice after traumatic brain injury through targeting Rela/ApoE signaling pathway." (PMID 36311808, 2022).
colorectal adenocarcinoma (1 paper, 2022). The most common type of colorectal carcinoma. "Among the genes associated with mbesQTLs and known to be differently expressed in colorectal adenocarcinoma tissue according to The Cancer Genome Atlas database, USP14, LOXL2 (lysyl oxidase-like 2) and TP63 (tumor protein 63) link the microbiota composition with cancer development." (PMID 35794137, 2022).
colorectal tumor (1 paper, 2023). "The IHC results revealed that USP14 was upregulated in colorectal tumor tissues compared with benign tissue." (PMID 36693850, 2023). "We sought to examine the role of USP14 in colorectal tumor development." (PMID 36693850, 2023).
endometrial adenocarcinoma (1 paper, 2016). "In this study, we show that higher expression levels of USP14 are independently associated with recurrence in a retrospective cohort of women with stage I endometrial adenocarcinoma." (PMID 27121063, 2016). "Collectively, our experiments support the notion that USP14 shows promise as a potential biomarker for recurrent disease and that inhibition of USP14 may be of therapeutic benefit for women with endometrial adenocarcinoma." (PMID 27121063, 2016).
endothelial dysfunction (1 paper, 2022). In vascular diseases, endothelial dysfunction is a systemic pathological state of the endothelium (the inner lining of blood vessels) and can be broadly defined as an imbalance between vasodilating and vasoconstricting substances produced by (or acting on) the endothelium. "In endothelial cells, UCA1 formed a ternary complex with USP14 and PFN1, prolonged the half-life of the PFN1 protein, and subsequently activated the RhoA/ROCK pathway to produce excess ROS and induce endothelial dysfunction." (PMID 36160709, 2022).
esophageal cancer (1 paper, 2024). A primary or metastatic malignant neoplasm involving the esophagus. "Our findings suggested that PKCiota suppressed the ferroptosis of esophageal cancer cells by stopping the USP14-mediated autophagic degradation of GPX4." (PMID 38247539, 2024). "PKCiota was negatively regulated by miR-145-5p, which decreased in esophageal cancer, and also regulated by USP14 and GPX4 by a positive feedback loop." (PMID 38247539, 2024).
follicular thyroid cancer (1 paper, 2023). "In this work, we have investigated USP14 expression and cell responses towards the inhibitor, IU1 using ML1 cells as an in-vitro model for human follicular thyroid cancer." (PMID 37711852, 2023).
hepatitis C virus infection (1 paper, 2025). A viral infection caused by the hepatitis C virus. "For example, silencing USP18 has been shown to promote the antiviral innate immunity against hepatitis C virus infection, while pharmacological inhibition of USP14 greatly suppresses murine norovirus infection." (PMID 40208866, 2025).
liver fibrosis (1 paper, 2023). "We further evaluated the role of USP14 in the HFHC diet-induced NASH model, which exhibited a more severe inflammatory response and liver fibrosis than the HFD model." (PMID 37633951, 2023).
mastitis (1 paper, 2022). Inflammation of breast tissue during lactation or postpartum due to an obstructed duct or infection. "In our study, we found that IL-6 could induce ferroptosis of mammary epithelial cells, and inhibition of IL-6 by USP14 knockdown suppressed ferroptosis, suggesting a novel contribution manner of IL-6 in mastitis." (PMID 35549778, 2022).
mixed glioma (1 paper, 2023). A tumor composed of two or more glial cell types (astrocytes, ependymal cells, and oligodendrocytes). "Of note, differential expression of USP14 was also observed in mixed gliomas and in EPN." (PMID 37892185, 2023).
Neurodevelopmental delay (1 paper, 2025). "Disruption of USP14 can lead to profound ID, spasticity, hypotonia, and neurodevelopmental delay (NDD)." (PMID 40243517, 2025).
oral cancer (1 paper, 2023). "Previous studies have demonstrated that USP14 is highly expressed in oral cancer and promotes radio-resistance by regulating autophagy." (PMID 37055579, 2023).
osteoarthritis (1 paper, 2023). A noninflammatory degenerative joint disease occurring chiefly in older persons, characterized by degeneration of the articular cartilage, hypertrophy of bone at the margins and changes in the synovial membrane. "USP14 was highly elevated in osteoarthritis articular cartilage and IL-1β-induced chondrocytes." (PMID 37359559, 2023). "Hence, USP14 might be a useful target for osteoarthritis intervention." (PMID 37359559, 2023).
pneumonia (1 paper, 2024). An acute, acute and chronic, or chronic inflammation focally or diffusely affecting the lung parenchyma, caused by an infection in one or both of the lungs (by bacteria, viruses, fungi, or mycoplasma.). "Several studies have reported that USP11 and USP14 contribute to the aggravation of inflammation in LPS-induced pneumonia." (PMID 38322269, 2024). "For example, QingFeiPaiDu decoction and wogonoside have been reported to reduce USP14 levels, thereby alleviating pneumonia." (PMID 38322269, 2024). "Furthermore, USP14 plays a proinflammatory role in pneumonia." (PMID 38322269, 2024).
primary brain tumors (1 paper, 2023). "We identified a selected group of DUBs (USP13, USP14, USP19, USP25, OTUD2/YOD1) associated with the Regulation of ERAD pathway across several adult and pediatric primary brain tumors (GBM, EPN, CPh, MB)." (PMID 37892185, 2023).
rectal cancer (1 paper, 2024). A primary or metastatic malignant neoplasm that affects the rectum. "In rectal cancer, Usp14 (ubiquitin-specific peptidase 14) deubiquitinates and stabilizes JNK, thereby promoting MAPK/JNK signaling cascade activation." (PMID 38594767, 2024).